PAQR8 (progestin and adipoQ receptor family member 8)
Description:
Plasma membrane progesterone (P4) receptor coupled to G proteins. Seems to act through a G(i) mediated pathway. May be involved in oocyte maturation (By similarity). Also binds dehydroepiandrosterone (DHEA), pregnanolone, pregnenolone and allopregnanolone.
Synonyms: C6orf33; LMPB1; MPRB
Tractability: Antibody: UniProt places it where antibodies can reach, with high confidence; its Gene Ontology location is reachable by antibodies, with high confidence; UniProt predicts a signal peptide or a membrane-spanning region; the Human Protein Atlas places it where antibodies can reach.
Gene: Protein-coding gene on chromosome 6 (52,361,421 to 52,407,777, forward strand). Ensembl gene ENSG00000170915.
Subcellular location: Cell membrane
Subcellular location (Human Protein Atlas): Plasma membrane; Golgi apparatus
Gene Ontology:
Molecular function: protein binding; nuclear steroid receptor activity; steroid binding
Biological process: response to steroid hormone; nuclear receptor-mediated steroid hormone signaling pathway
Cellular component: plasma membrane; membrane
Genetic constraint (gnomAD): Loss-of-function variants: 17 observed, 26.23 expected, observed/expected ratio (o/e) 0.65, 90% interval 0.44 to 0.97. The upper end of that interval is the gene's LOEUF score, 0.97, which puts it in group 4 of 6, group 1 being the genes least tolerant of losing a copy. Missense variants: 392 observed, 471.32 expected, observed/expected ratio (o/e) 0.83, 90% interval 0.76 to 0.9. Synonymous variants: 204 observed, 199.34 expected, observed/expected ratio (o/e) 1.02, 90% interval 0.91 to 1.15.
Homologues: Orthologues: chimpanzee PAQR8 (100% identical), macaque PAQR8 (99% identical), rabbit PAQR8 (97% identical), dog PAQR8 (97% identical), rat Paqr8 (95% identical), mouse Paqr8 (94% identical), guinea pig PAQR8 (93% identical), pig PAQR8 (91% identical), tropical clawed frog paqr8 (69% identical), zebrafish paqr8 (55% identical), Caenorhabditis elegans K11C4.2 (18% identical), Drosophila melanogaster AdipoR (18% identical), and 1 more. Paralogues in human: PAQR7 (46% identical), PAQR6 (27% identical), PAQR5 (25% identical), ADIPOR2 (21% identical), ADIPOR1 (20% identical), PAQR9 (18% identical), PAQR3 (18% identical), PAQR4 (17% identical), MMD2 (13% identical), MMD (11% identical).
Diseases named in the same sentence as PAQR8 in open-access papers:
PAQR8 is named in the same sentence as 23 diseases in open-access papers, as found by Europe PMC text mining. Sharing a sentence is not in itself a finding about the gene and the disease. The quoted sentences say what the papers report.
breast cancer (4 papers, 2022 to 2025). A primary or metastatic malignant neoplasm involving the breast. "Reviewing the relationship between partial dormancy factors and WNT signaling, PAQR8 expression has been shown to reduce WNT1 activity in HER2+ breast cancer models, while the loss of NR2F1 activates WNT signaling and subsequently inhibits E-cadherin expression." (PMID 40977686, 2025). "Of particular interest, PAQR8 gene expression has been identified as both necessary and sufficient for effective breast cancer recurrence in mice." (PMID 40977686, 2025). "When compared to our findings in breast cancer patients, we found a striking similarity in the pattern of preferential enrichment for Paqr8 CN gain in recurrent, compared to primary, tumors across these GEM models." (PMID 36597146, 2023). "Together, these observations indicate that Paqr8 is both necessary and sufficient for efficient mammary tumor recurrence following downregulation of the Her2 pathway." (PMID 36597146, 2023). "We recently identified copy number (CN) gain of the putative membrane progesterone receptor PAQR8 as one of four focal CN alterations that preferentially occurred in recurrent metastatic tumors compared to primary tumors in breast cancer patients." (PMID 36597146, 2023). "Having demonstrated that Paqr8 is both necessary and sufficient for efficient breast cancer recurrence, we wished to identify the stages of tumor regression, cellular dormancy, and recurrence during which Paqr8 plays a role." (PMID 36597146, 2023). "In aggregate, our studies provide in vivo evidence that PAQR8 plays a functional role in cancer, implicate PAQR8, ceramide metabolism, and cAMP in breast cancer recurrence, and identify a novel mechanism of resistance to multiple antineoplastic therapies." (PMID 36597146, 2023). "Together, our data support a model in which PAQR8 promotes breast cancer recurrence by facilitating resistance to multiple antineoplastic therapies in a manner that alters ceramide levels and requires coupling to a Gi protein." (PMID 36597146, 2023). "To extend these findings to pharmacological inhibition of Her2 in human breast cancer cells, we overexpressed PAQR8 in BT474-M1 cells, a Her2+/ER+ human breast cancer cell line." (PMID 36597146, 2023). "To test this hypothesis, we overexpressed PAQR8 in MCF7 cells, an ER+ human breast cancer cell line with low endogenous expression of PAQR8." (PMID 36597146, 2023). "We used orthotopic mouse models to determine whether PAQR8 overexpression or deletion alters breast cancer dormancy or recurrence following therapy." (PMID 36597146, 2023). "Together, these findings suggest that PAQR8 promotes breast cancer cell resistance to chemotherapy." (PMID 36597146, 2023). "To investigate this hypothesis, we tested the effects of PAQR8 overexpression or PAQR8 deletion on the response to treatment with doxorubicin or docetaxel, chemotherapeutic agents commonly used in treating breast cancer patients." (PMID 36597146, 2023). "Consistent with a clinically relevant role in breast cancer, we found that PAQR8 is spontaneously upregulated and CN gained in post-therapy recurrent tumors from multiple mouse models and is associated with breast cancer progression and poor survival in patients." (PMID 36597146, 2023). "In this study, we examined the role of PAQR8 in breast cancer recurrence and resistance to therapy." (PMID 36597146, 2023). "Given that STK11/LKB1, CDKN2A, and PTK6 each have well-described roles in cancer progression, we hypothesized that PAQR8 might play a role in breast cancer recurrence." (PMID 36597146, 2023). "Our data provide in vivo evidence that PAQR8 plays a functional role in cancer, implicate PAQR8, cAMP, and ceramide metabolism in breast cancer recurrence, and identify a novel mechanism that may commonly contribute to the acquisition of treatment resistance in breast cancer patients." (PMID 36597146, 2023).
breast cancer (continued). "Given the parallel pattern of enrichment for PAQR8 CN gain in recurrent tumors in both humans and mice, along with the observed upregulation of Paqr8 during tumor recurrence in GEM models, we asked whether PAQR8 promotes breast cancer recurrence." (PMID 36597146, 2023).
endometriosis (4 papers, 2020 to 2025). The growth of functional endometrial tissue in anatomic sites outside the uterine body. "In humans, the decreased expression of PAQR8 is associated with resistance to progesterone in patients suffering from endometriosis." (PMID 37108601, 2023). "The analysis of gene expression showed that PAQR7 and PAQR5 expression was lower in both eutopic and ectopic endometrium as compared to the endometrium of women without endometriosis, whereas the expression of PAQR8 and PAQR6 was only reduced in eutopic endometrium." (PMID 32733932, 2020). "Using RT-qPCR, we observed that the expression of PAQR7, PAQR8, PAQR5, and PAQR6 genes was significantly downregulated in the eutopic endometrium of patients with endometriosis compared with the endometrium of women without the disease." (PMID 32733932, 2020).
endometrial cancer (3 papers, 2020 to 2022). Primary or metastatic malignant neoplasm involving the endometrium (mucous membrane that lines the endometrial cavity). "In addition, PAQR7 and PAQR8 expression and the respective protein content are decreased in endometrial cancer compared to adjacent nonaffected endometrium, whereas mPRγ protein content is increased in endometrial cancer tissue." (PMID 32733932, 2020).
adenomyosis (1 paper, 2022). The growth of endometrial tissue inside the muscular wall of the uterine corpus. "The expression of PAQR7 (mPRα) and PAQR8 (mPRβ) was significantly upregulated in adenomyosis compared to normal myometrium." (PMID 35956024, 2022).
Cerebral ischemia (1 paper, 2022). Restriction of arterial blood supply to the brain associated with insufficient oxygenation to support the metabolic requirements of the tissue. "One study suggested that baicalin and/or jasminoidin alleviated cerebral ischemia through upregulating PAQR8 expression in the rat hippocampus." (PMID 36582228, 2022).
Coronary artery atherosclerosis (1 paper, 2025). "Coronary artery atherosclerosis (LAD-lesion area) was positively correlated with WDR62 and MARS1 transcript levels, and negatively correlated with FGGY, PAQR8, and RPS20 transcript levels (p < 0.05)." (PMID 40709334, 2025).
prostate carcinoma (1 paper, 2021). A carcinoma that arises from epithelial cells of the prostate gland. "On the other hand, PAQR8 expression was negatively regulated by AR signaling and correlated with NEPC progression after ADT/AR antagonist treatment in prostate cancers." (PMID 34572596, 2021).
cancer (3 papers, 2021 to 2023). A tumor composed of atypical neoplastic, often pleomorphic cells that invade other tissues. "We also found a reversal event for PAQR8 downregulation in primary cancers but an upregulation in NEPC tumors." (PMID 34572596, 2021).
tumor (2 papers, 2023 to 2024). "Expression of mRNA encoding PAQR7 and PAQR8 in a panel of OC cell lines was below the qPCR detection limit and was downregulated in tumour tissue samples, whereas high expression of PGRMC1 and PAQR4 mRNA was observed in rare subtypes of OC cell lines." (PMID 39464509, 2024). "Quantification of the eGFP to mCherry ratio following Her2 downregulation revealed progressive enrichment for eGFP-expressing Paqr8-OE cells across multiple stages of tumor progression, eventually resulting in recurrent tumors with > 90% Paqr8-OE cells." (PMID 36597146, 2023). "Paqr8-overexpressing (Paqr8-OE) or control tumor cells were orthotopically injected into athymic nude (nu/nu) mice maintained on doxycycline." (PMID 36597146, 2023). "Together, these in vivo and in vitro findings consistently and concordantly indicate that Paqr8 confers a selective advantage on tumor cells following Her2 downregulation, particularly during the initial phase of response to therapy." (PMID 36597146, 2023). "Together, these observations reveal a role for PAQR8 in mediating resistance to multiple types of therapy, which in turn can promote tumor recurrence." (PMID 36597146, 2023). "Next, we conducted analogous experiments to determine the effects of Paqr8 deletion (Paqr8-KO) on the rate of tumor recurrence." (PMID 36597146, 2023). "This indicates that Paqr8 is sufficient to accelerate the rate of tumor recurrence following Her2 downregulation." (PMID 36597146, 2023). "Primary tumor formation and regression for Paqr8-OE and control cells occurred with equivalent kinetics." (PMID 36597146, 2023). "The greatest rate of enrichment for Paqr8-OE cells was observed from primary tumors to day 10 of tumor regression (p < 0.0001), during which the bulk of tumor cells die following acute Her2 downregulation." (PMID 36597146, 2023). "Further selection for Paqr8-OE, and against Paqr8-KO, tumor cells was observed from D7 to D28 of the dormancy period." (PMID 36597146, 2023). "This, in turn, suggests that the competitive advantage conferred on tumor cells by Paqr8 following Her2 downregulation is principally mediated by effects of Paqr8 on tumor cell survival." (PMID 36597146, 2023). "We therefore performed immunofluorescence for markers for apoptosis (cleaved caspase-3), cell cycle (Ki67), and S-phase (EdU) in Paqr8-OE and Paqr8-KO tumor cells following Her2 downregulation in vivo and in vitro." (PMID 36597146, 2023). "Together, these results indicate that Paqr8 provides a selective advantage to tumor cells in vivo following acute Her2 downregulation, as well as during dormancy and tumor recurrence." (PMID 36597146, 2023). "Conversely, in the absence of Her2 expression Paqr8-KO cells formed significantly fewer colonies than controls (p = 0.010), paralleling the decreased rate of recurrence observed for Paqr8-KO tumor cells in mice." (PMID 36597146, 2023). "Consistent with our prior results, we observed an increase in viable Paqr8-OE tumor cells, as well as a decrease in viable Paqr8-KO tumor cells, compared to controls following Her2 downregulation for 72 h." (PMID 36597146, 2023). "To address this, we measured cAMP levels in mouse Paqr8-OE and Paqr8-KO Her2-dependent primary tumor cells following acute Her2 downregulation, conditions under which Paqr8 exerts a pro-survival effect." (PMID 36597146, 2023). "This parallels the increased rate of recurrence observed for Paqr8-OE tumor cells in mice." (PMID 36597146, 2023). "Together, the congruent effects of Paqr8 overexpression and deletion in vivo and in vitro reinforce the conclusion that Paqr8 is both necessary and sufficient for tumor recurrence in the setting of Her2 inhibition, either by genetic downregulation or by pharmacological inhibition." (PMID 36597146, 2023).
tumor (continued). "To determine whether the observed changes in cAMP levels were mediated by a Gi protein-coupled receptor, we preincubated Paqr8-OE or Paqr8-KO tumor cells with pertussis toxin (PTX) prior to measuring forskolin-stimulated levels of cAMP." (PMID 36597146, 2023). "In addition, in the presence of Her2 expression, both Paqr8-OE and Paqr8-KO tumor cells exhibited levels of staining for apoptotic and proliferative markers that were similar to their respective controls." (PMID 36597146, 2023). "The competitive advantage exhibited by Paqr8-OE, and competitive disadvantage exhibited by Paqr8-KO, tumor cells following Her2 downregulation could potentially result from Paqr8-mediated differences in cell survival, proliferation, or both." (PMID 36597146, 2023). "To begin to query whether PAQR8 might function as a ceramidase, we analyzed the sphingolipidome of Paqr8-OE and Paqr8-KO Her2-dependent primary tumor cells 72 h after Her2 downregulation using liquid chromatography-high resolution mass spectrometry (LC-HRMS)." (PMID 36597146, 2023). "To do this, we engineered Her2-dependent primary tumor cells derived from the MMTV-rtTA;TetO-Her2 inducible GEM model mice to either overexpress Paqr8 or delete Paqr8 using CRISPR-cas9." (PMID 36597146, 2023). "Significant positive selection for Paqr8-OE (p = 0.029), and negative selection against Paqr8-KO (p = 0.004), tumor cells occurred from D0 to D7, during which time cells undergo apoptosis in response to acute Her2 inhibition." (PMID 36597146, 2023). "In addition, these in vitro findings indicate that the effects of Paqr8 on Her2-independent growth are tumor cell autonomous, do not require stromal or host immune cells, and occur in both human and mouse cells." (PMID 36597146, 2023). "An analysis of PAQR8 transcript levels in the GEPIA database revealed that expression of this gene in OC tissue is significantly lower than in normal tissue (p ≤ 0.05); however, expression was not related to the tumour stage or survival rates." (PMID 39464509, 2024).
PAQR8 also shares sentences with these, for which no sentence is quoted: infection (3 papers); latent infection (2); neuroblastoma (2); ovarian carcinoma (2); adrenal pheochromocytoma (1); brain diseases (1); colorectal cancer (1); glioblastoma (1); hepatic angiosarcoma (1); liver cancer (1); major depression (1); metastatic tumors (1); Stroke (1); undifferentiated pleomorphic sarcoma (1).